GPR39 (G protein-coupled receptor 39)
Diseases named in the same sentence as GPR39 in open-access papers (continued):
Sharing a sentence is not in itself a finding about the gene and the disease.
cancer (9 papers, 2011 to 2024). A tumor composed of atypical neoplastic, often pleomorphic cells that invade other tissues. "Changes in the expression of ZnR/GPR39 were previously associated with more aggresive cancers." (PMID 29802348, 2018). "Increased levels of GPR39 were revealed in the central nervous system during aging and in various types of cancer." (PMID 39684342, 2024). "More evidence of a role for ZnR/GPR39 activation in cancer progression comes from work showing that it regulates several important ion transporters thought to play a role in cell survival and proliferation." (PMID 34572390, 2021). "Increased cell proliferation and migration, as well as the activation of MAPK and AKT, suggest a possible role for ZnR/GPR39 in cancer." (PMID 29389900, 2018). "Future studies aiming to specifically test the role of ZnR/GPR39 in cancer tissue and the link to ZIP transporters expression are of major interest and can provide a novel target for therapeutic tools." (PMID 29389900, 2018). "Thus, ZnR/GPR39 represents a highly viable target for new molecular or immune approaches to hormone-resistant cancers and TNBC." (PMID 34572390, 2021). "Interestingly, cytoplasmic Zn2+ levels in the prostate are high, and expression of the ZnR/GPR39 in non-cancer cells was very low, likely due to desensitization of the receptor." (PMID 34572390, 2021). "Our results indicate that ZnR/GPR39 signaling, triggered by extracellular Zn2+, leads to activation of the MAPK and PI3K/AKT pathways, both closely associated with cell growth and survival in cancer." (PMID 29802348, 2018). "The increase in ZnR/GPR39 level in more aggresive cancer cells taken together with such transient Zn2+ changes may therefore play a role in enhanced growth and invasiveness." (PMID 29802348, 2018). "In androgen-insensitive prostate cancer cell lines, ZnR/GPR39 activation by Zn2+ triggers PI3K pathway upregulation, which is reflected by increased expression and phosphorylation of AKT, associated with more malignant phenotypes of carcinomas." (PMID 29389900, 2018). "In this context, obestatin, a 23-amino acid peptide derived from the ghrelin peptide precursor (preproghrelin), was originally identified in the stomach, and its receptor, GPR39, was demonstrated to exert a pivotal role in many physiological functions and in multiple diseases, including cancer." (PMID 26716511, 2016). "Emerging evidence indicates that G protein-coupled receptors are crucial players in cancer progression and metastasis, however, the role of GPR39 in cancer development remains unclear." (PMID 21352519, 2011). "Functional studies showed that GPR39 could effectively promote ESCC cancer cell growth, increase foci formation and colony formation and enhance tumor formation in nude mice." (PMID 21352519, 2011). "Other studies that associated ZnR/GPR39 expression in epithelial cells with cancer did not employ changes in extracellular or dietary Zn2+ to specifically study whether signaling pathway activation or Zn2+-dependent processes are affected in the cancer cells." (PMID 29389900, 2018). "A better understanding of the molecular mechanism of GPR39 in ESCC development and progression would provide novel therapeutic strategies to ESCC cancer patients." (PMID 21352519, 2011).
tumor (4 papers, 2009 to 2019). "To investigate the level of expression and the potential role of GPR39 in HCC tissues, we conducted qRT‐PCR and WB assays, and the results showed that GPR39 levels were much lower in adjacent non‐tumour tissues than in HCC tissues (P < .05)." (PMID 31576658, 2019). "In that sense, the correlation found for GPR39 and the histologic type endorse the use of this receptor as a marker of tumor progression." (PMID 26716511, 2016). "The tumorigenic function of GPR39 was assessed by both in vitro and in vivo assays including foci formation, colony formation in soft agar, cell growth rate assays and tumor xenograft experiment." (PMID 21352519, 2011). "The results showed that the tumor growth curve of GPR39-overexpressing cells was significantly increased compared to Vec-30 cells (P < 0.01)." (PMID 21352519, 2011). "Another interesting finding of this study is the promoting effect of GPR39 on tumor metastasis in ESCC." (PMID 21352519, 2011). "In this study, we have also provided evidence that targeting of GPR39 with specific RNAi will reduce the oncogenic characteristics of ESCC tumor cells." (PMID 21352519, 2011). "Moreover, in clinical samples, we discovered that the expression of GPR39 was dramatically lower in high miR‐1914 expression tumours than in low miR‐1914 expression tumours (P < .05)." (PMID 31576658, 2019). "Thus, cytoskeleton reorganization induced by obestatin/GPR39, shifting its epithelial phenotype to an invasive-like one, facilitated tumor migration, invasion, and metastasis." (PMID 26716511, 2016). "We found that GPR39 has some impact on the EMT as shown by decreasing the epithelial molecule E-cadherin, an event critical in tumour invasion and a 'master' regulator of EMT." (PMID 21352519, 2011). "Introduction of GPR39 gene into ESCC cell line KYSE30 could promote cell proliferation, increase foci formation, colony formation in soft agar, and tumor formation in nude mice." (PMID 21352519, 2011).
intestinal diseases (2 papers, 2022 to 2023). "Therefore, using GPR39 as a target to investigate the role of Zn2+ in the animal intestinal tract will provide new directions and ideas for the prevention and treatment of animal intestinal diseases." (PMID 36292986, 2022).
adenocarcinoma (1 paper, 2016). A common cancer characterized by the presence of malignant glandular cells. "A particularly interesting result is that chief cells expressed GPR39 together with the expression found in human adenocarcinomas." (PMID 26716511, 2016). "In this study, we determined the role of the obestatin/GPR39 system in regulating motility, EMT, and invasion of adenocarcinoma cells." (PMID 26716511, 2016).
infection (1 paper, 2018). The state of being infected such as from the introduction of a foreign agent such as serum, vaccine, antigenic substance or organism. "Infection of the cells with the lentiviral constructs abolished the Zn2+-dependent Ca2+ responses in shGPR39 TAMR cells, but not in the shSCR cells infected with a scrambled construct, suggesting that ZnR/GPR39 signaling is absent in the shGPR39 cells." (PMID 29802348, 2018).
myopathies (1 paper, 2026). "Previously, we demonstrated the potential of obestatin, a peptide derived from preproghrelin, and the G‐protein coupled receptor, GPR39 (the obestatin/GPR39 system), as therapeutic target for muscle injury and myopathies related to skeletal muscle regeneration." (PMID 41541654, 2026).
neurodegenerative disease (1 paper, 2021). A disorder of the central nervous system characterized by gradual and progressive loss of neural tissue and neurologic function. "Therefore, GPR39 has been proposed as a potential therapeutic target for ischemia/reperfusion injury and neurodegenerative diseases." (PMID 34645465, 2021).
neurological diseases (1 paper, 2023). "This review focuses on the mechanism of action of GPR39 in vivo and ex vivo, associated signaling pathways, and important roles of these factors in different neurological diseases and summarizes recent findings in GPR39 agonists." (PMID 36942516, 2023). "GPR39 and its associated diseases are summarized, particularly on recent studies on neurological diseases." (PMID 36942516, 2023). "In the near future, GPR39 can be a target in neurological diseases for targeted therapy, which will help doctors overcome the associated problems." (PMID 36942516, 2023). "GPR39 can be a promising target in neurological diseases for targeted therapy, which will help doctors overcome the associated problems." (PMID 36942516, 2023). "This review aims to provide an overview of the functions, signal transduction pathways, and pathophysiological role of GPR39 in neurological diseases and summarize the GPR39 agonists that have been identified in the recent years." (PMID 36942516, 2023). "Future studies investigating whether GPR39 agonists can selectively activate GPR39‐dependent signaling pathways would provide new ideas and targets for the treatment of currently incurable neurological diseases." (PMID 36942516, 2023). "In‐depth studies of the mechanism of GPR39 may reveal GPR39 as a target for future drug treatments for neurological diseases." (PMID 36942516, 2023).
GPR39 also shares sentences with these, for which no sentence is quoted: psychiatric disorder (3 papers); alcohol use disorder (2); cardiovascular diseases (2); Seizure (2); type 2 diabetes (2); Atrophy (1); bone disorder (1); breast tumor (1); Calcific aortic valve disease (1); Cerebral ischemia (1); gastrointestinal stromal tumor (1); gout (1); heart failure (1); ischemia (1); lung carcinoma (1); metabolic syndrome (1); myocardial ischemia (1); overactive bladder (1); pulmonary arterial hypertension (1); renal carcinoma (1); Salmonella Infections (1); sleep disorder (1); white matter hyperintensities (1).